PAK4 (p21 (RAC1) activated kinase 4)
Diseases named in the same sentence as PAK4 in open-access papers (continued):
Sharing a sentence is not in itself a finding about the gene and the disease.
colon cancer (15 papers, 2014 to 2025). "PAK4 overexpression is associated with poor prognosis in gastric tumours, non-small cell lung cancer, oral squamous cell carcinoma, colon cancer and clear cell renal carcinoma." (PMID 37761312, 2023). "In this prior work, the effects in prostate and colon cancer cells were consistent with the role of FRAT1 in preventing the association of GSK-3β with the destruction complex, while the downregulation of PAK4 inhibited nuclear translocation of β-catenin." (PMID 38815861, 2024). "Studies found that inhibition of PAK4 and PAK1 suppresses the KRAS and BRAF mutation in colon cancer in vitro." (PMID 35409064, 2022). "We also verified the potential role of RSK2 and PAK4 in 5‐FU chemoresistance in DLD‐1 colon cancer cells." (PMID 36045417, 2022). "For example, miR-9-5p can target PAK4 to repress the proliferation and inhibit the apoptosis of colon cancer cells; in cervical cancer, miR-9-5p can regulate the angiogenesis and radiosensitivity of cervical cancer cells by targeting SOCS5." (PMID 33776787, 2021). "PAK4 status in colon tissue from patients with colon cancer is positively correlated with the level of G6PD." (PMID 31500396, 2019). "MiR-145 inhibits colon cancer cell migration and invasion through post-transcriptional suppression of p21-activated kinase 4 (PAK4)." (PMID 31887997, 2019). "The results showed that PAK4 expression was positively correlated with G6PD expression (P=0.041) in colon cancer tissues." (PMID 28542136, 2017). "The results were consistent with our findings that PAK4 upregulated G6PD activity in colon cancer cell lines." (PMID 28542136, 2017). "We also found that PAK4 level was significantly increased in 113 out of 154 patients with colon cancer." (PMID 28542136, 2017). "We demonstrate a novel glucose metabolism-related mechanism of PAK4 in promoting the colon cancer cell growth." (PMID 28542136, 2017). "Due to the pivotal role of PAK4 as key regulator in cancer cell signaling networks, we sought to specifically probe the role of PAK4 in regulating the colon cancer cell metabolism and proliferation." (PMID 28542136, 2017). "In another important observation, an essential role of PAK4 in K-Ras driven proliferation and colony formation ability of colon cancer cells was also established." (PMID 25238288, 2014). "Interestingly, when PAK4 and PAK1 were treated simultaneously, only PAK4 responded for seven colon cancer cell lines in the cell proliferation assay." (PMID 35409064, 2022). "There has been evidence that PAK4 drives prostate and colon cancer cells to metastasize." (PMID 33138288, 2020). "Overexpression of PAK4 in colon cancer cells enhances glucose and NADPH production." (PMID 31500396, 2019). "Notably, we showed that there was a strong positive correlation between PAK4 and G6PD expression in colon cancer specimens and that the expression of PAK4 or G6PD was positively correlated with an aggressive phenotype of clinical colon cancer." (PMID 28542136, 2017). "Furthermore, expression of PAK4 or G6PD was positively correlated with an aggressive phenotype of clinical colon cancer." (PMID 28542136, 2017). "Besides PC, PAK4 overexpression has also been reported for several other tumor types including ovarian, breast, gastric and colon tumors suggesting its important roles in tumor development." (PMID 25238288, 2014). "Because the raw materials of lipid biosynthesis primarily come from glucose, so we hypothesized that PAK4 overexpression in colon cancer cells may use lipid biosynthesis to support the increased proliferation by directing glucose towards the biosynthetic processes." (PMID 28542136, 2017). "ABT-737 is a small-molecule inhibitor that represses Bcl-2/Bcl-XL, resulting in the inhibition of RNAi of PAK4 and PAK1 in HCT116 colon cancer cells." (PMID 35409064, 2022).
colon cancer (continued). "As a result, further investigation identified that PAK4 and PAK1 suppression were responsible for 95% and 80% cell proliferation, respectively, in HCT116 colon cancer cell lines alone." (PMID 35409064, 2022). "We also performed immunohistochemical staining of PAK4 and G6PD in 154 cases with colon cancer to confirm this observation." (PMID 28542136, 2017). "In this study, we reported that PAK4 promoted glucose intake, NADPH production and lipid biosynthesis, leading to an increased proliferation of colon cancer cells." (PMID 28542136, 2017). "Taken together, these results suggested that PAK4 promoted glucose consumption and NADPH production in colon cancer cells via increasing the enzyme activity of G6PD." (PMID 28542136, 2017). "PAK4 and G6PD were highly expressed in 50% (13/26) and 61.5% (16/26) of colon cancer samples, respectively." (PMID 28542136, 2017). "Through screen and subsequent validation, we reveal substrates of RSK2 and PAK4 kinases as main effectors in responding to 5‐FU chemotherapy, and combinational treatment of colon cancer cells with 5‐FU and RSK2 inhibitor or PAK4 inhibitor can largely inhibit cell growth and enhance cell apoptosis." (PMID 36045417, 2022). "The levels of G6PD and PAK4 were increased in colon cancer tissue samples compared with adjacent noncancerous tissue samples." (PMID 28542136, 2017). "Importantly, for the first time, we established a correlation between PAK4 and G6PD in colon cancer with clinicopathological analysis." (PMID 28542136, 2017). "Unlike noncancerous tissues, high expression levels of G6PD and PAK4 were observed in colon cancer tissues (right)." (PMID 28542136, 2017). "In addition, we demonstrated a close positive correlation between PAK4 and G6PD expression in colon cancer specimens." (PMID 28542136, 2017). "Therefore, inhibition of PAK4 and/or G6PD activity might be a potential therapeutic strategy for colon cancer." (PMID 28542136, 2017). "Similar to the recent findings in pancreatic acinar cells with PAK4, PAK4 activation was independent of PI3K/Akt activation in colon cancer cells." (PMID 40001881, 2025). "However, despite PAK4 leading to Mek/ERK activation in pancreatic acinar cells, this is not the case in colon cancer cells where the Raf/Mek/ERK pathway is independent of PAK4 activation." (PMID 40001881, 2025).
glioblastoma (13 papers, 2017 to 2025). The most malignant astrocytic tumor (WHO grade IV). "Among the group II PAK isoforms, PAK4 is linked to glioblastoma cell proliferation, senescence, and migration, corroborating the connection to glioblastoma therapy resistance." (PMID 35883575, 2022). "Research has shown that blood vessels in glioblastomas, a highly vascularized and immune-resistant solid tumor, express p21-activated kinase 4 (PAK4), an enzyme involved in regulating genetic reprogramming and abnormal vascularization." (PMID 40173050, 2025). "In a kinome-wide screening of mesenchymal-like transcriptional activation in human glioblastoma-derived endothelial cells, PAK4 was identified as a selective regulator of genetic reprogramming in tumour vasculature, leading to aberrant vascularisation." (PMID 38067120, 2023). "In conclusion, we demonstrate a so-far undescribed function of PAK4 in regulating glioblastoma cell radiosensitivity through the modulation of DNA damage repair mechanisms." (PMID 35883575, 2022). "A study on glioblastoma suggested that PAK4 was down-regulated by miR-485 and inhibited the malignant biological behavior of glioblastoma cells." (PMID 35842733, 2022). "Overall, our study provides functional evidence for a PAK4-dependent modulation of DNA repair mechanisms leading to radioresistance in glioblastoma cells." (PMID 35883575, 2022). "To validate PAK4 as a central determinant of clonogenic radiation survival, we extended our knockdown analysis to a panel of five glioblastoma cell lines." (PMID 35883575, 2022). "p21-activated kinase 4 (PAK4) was identified as a selective regulator of genetic reprogramming and aberrant vascularization in glioblastoma-derived endothelial cells." (PMID 35203517, 2022). "The PAK4/YAP pathway is the main downstream signaling pathway of integrin β3 driving Glut3 expression to promote glioblastoma progression." (PMID 35805163, 2022). "Our study is the first to demonstrate the potential of PAK4 targeting for glioblastoma radiosensitization." (PMID 35883575, 2022). "Of all six isoforms, PAK4 appears to play the most important role in the radiosensitivity and invasion of glioblastoma cells." (PMID 35883575, 2022). "In conclusion, our data suggest PAK4 as a putative target for radiosensitization and impairing DNA repair in glioblastoma, deserving further scrutiny in extended combinatorial treatment testing." (PMID 35883575, 2022). "PAK4 appears to be functionally associated with the migration, invasion, and EMT of glioblastoma cells and is involved in preventing senescence-linked cell cycle arrest and proliferation." (PMID 35883575, 2022). "In a siRNA-based screen targeting all PAK isoforms, we identified PAK4 to mediate both the invasion as well as radioresistance of glioblastoma cells." (PMID 35883575, 2022). "We focused our further analyses on potential mechanisms linking PAK4 to the glioblastoma radiation response." (PMID 35883575, 2022). "In vivo treatment of mice bearing EGFRvIII-expressing glioblastoma with the PAK4 inhibitor KPT9274 led to sensitization of the tumors to the cellular immunotherapy with enhanced tumor clearance and survival compared to CAR T cells or KPT9274 treatment alone." (PMID 35203517, 2022). "Here, we report a relationship between PAK4 and the cellular DNA damage response in glioblastoma cells, as PAK4 inhibition increases residual DSBs." (PMID 35883575, 2022). "Meanwhile, inhibition of PAK4 can normalize the tumor vascular microenvironment and sensitize glioblastoma (GBM) to chimeric antigen receptor–T (CAR-T) cell immunotherapy." (PMID 36105226, 2022). "This approach identified PAK4 as a critical determinant, as PAK4 knockdown and its pharmacological inhibition reduced both clonogenic radiation survival and invasion in a panel of human glioblastoma cell line models." (PMID 35883575, 2022).
glioblastoma (continued). "In a panel of human glioblastoma cell models, we identified PAK4 as the main PAK isoform regulating invasion and clonogenic survival upon irradiation and demonstrated the radiosensitizing potential of PAK4 inhibition." (PMID 35883575, 2022). "In contrast, it was found that αvβ3 expression escapes OIS in glioblastoma by activating PAK4 and that mice expressing β1-deficient tumors show reduced tumor burden and activation of senescence." (PMID 28273461, 2017). "Additionally, we applied the pharmacological PAK4 inhibitor PF-3758309 (PAK4i) to LN229 and U343MG cells to confirm the link between PAK4 and glioblastoma cell radiosensitivity." (PMID 35883575, 2022). "Hence, our data suggest PAK4 as a potential molecular target to overcome glioblastoma radioresistance." (PMID 35883575, 2022). "In addition, our data on PAK4-mediated collagen invasion are in line with recent studies suggesting a prominent role of PAK4 in regulating the progression of glioblastoma and metastasis in other cancer entities." (PMID 35883575, 2022). "Hence, our findings indicate an essential function of PAK4 in regulating glioblastoma radiosensitivity and proliferation." (PMID 35883575, 2022). "In glioblastoma (GBM), inhibition of PAK4 has induced intra-tumoral CD3+ T-cell infiltration, rendering GBM more susceptible to the immunotherapy of CAR-T cells." (PMID 38067120, 2023). "Through genetic screening, PAK4 is identified as a crucial regulator for proliferation, migration, invasion and permeability of glioblastoma-derived endothelial cells (GBM ECs)." (PMID 36105226, 2022). "A study revealed that inhibiting PAK4 can reprogram the tumor vasculature and improve the effectiveness of CAR T-cell therapy in glioblastoma." (PMID 40173050, 2025). "In agreement with our results, recent work by Fan and colleagues demonstrated that knocking out PAK4 in endothelial cells reorganize the whole tumor vascularity, increases immune cell infiltration and improves CAR-T cell therapy response in glioblastoma." (PMID 36588582, 2022). "PAK4 participates in the pentose phosphate pathway through G6PD, and PAK4 also promotes GLUT3 expression through YAP/TAZ and promotes glucose uptake by glioblastoma cells." (PMID 36230657, 2022). "In addition, it has been shown that deletion of the PAK4 gene in endothelial cells remodels the vascular microenvironment leading to increased T-cell infiltration and improved responses to chimeric antigen receptor (CAR)-T immunotherapy in glioblastoma." (PMID 36588582, 2022). "This became more relevant after Yi Fan's group demonstrated that blocking PAK4 expression in endothelial cells could reprogram the tumor vascular microenvironment, thus, facilitating the infiltration of CAR-T cells and improving the efficacy of immunotherapy in glioblastoma." (PMID 36588582, 2022).
colorectal cancer (12 papers, 2017 to 2025). A primary or metastatic malignant neoplasm that affects the colon or rectum. "In all OSCC patient tissue samples, immunohistochemical analysis revealed PAK4 expression in the cytoplasm, which was contrasted with the positive control colorectal carcinoma tissue." (PMID 38890401, 2024). "LncRNA IGFL2-AS1 was abundantly expressed in colorectal cancer tissues and cells, and comparatively bound to miR-433-3p to facilitate PAK4 transcription, thus promoting HCT116 cell malignant proliferation." (PMID 36620931, 2023). "For instance, miR-145 blocked the metastasis of human colorectal cancer cells through regulating PAK4-dependent pathway." (PMID 33563314, 2021). "MiR-145 inhibited human colorectal cancer cell migration and invasion through PAK4-dependent pathway." (PMID 30042169, 2018). "In addition, inhibition of PAK4 was presented as a therapeutic strategy for human cancers and PAK4 inhibitors showed antitumor activity in the breast, pancreas, and colorectal cancers." (PMID 36980457, 2023). "Next, we asked whether blockade of RSK2 or PAK4 activation can sensitize colorectal cancer cells to 5‐FU treatment." (PMID 36045417, 2022). "Furthermore, CDK15 is an upstream protein of PAK4 and functions as a regulator of PAK4 phosphorylation to elevate the activity of β-catenin and MEK/ERK signaling in colorectal cancer." (PMID 36105226, 2022).
glioma (12 papers, 2015 to 2025). A benign or malignant brain and spinal cord tumor that arises from glial cells (astrocytes, oligodendrocytes, ependymal cells). "In glioma, a nuclear association between PAK4 and the peroxisome proliferator-activated receptor gamma (PPARγ) regulates epithelial-to-mesenchymal transition, while PPARγ itself mediates the expression and function of DNA damage response genes." (PMID 35883575, 2022). "A recent study found that activation of anoikis in glioma cells was associated with inhibition of p21-activated kinase 4 (PAK4)." (PMID 36291283, 2022). "The results of immunohistochemistry and western blotting showed that PAK4 was more highly expressed in glioma tissues than in normal tissues, and the expression of PAK4 protein was positively correlated with the WHO grade." (PMID 40180890, 2025). "Divya Kesanakurti reported that PAK4 upregulation in gliomas and further determined its role in mesenchymal transition and radioresistance." (PMID 40180890, 2025). "Subsequently, the results of the TCGA and CGGA database analyses showed that PAK4 mRNA levels were greater in high-grade gliomas, and Kaplan‒Meier analysis of PAK4 indicated that patients with low PAK4 expression had longer survival." (PMID 40180890, 2025). "Similar results have been shown in glioma, where PAK4 expression intensifies with an increasing pathological grade." (PMID 35883575, 2022). "For example, miR-342–3p expression levels have been negatively correlated with advanced WHO grades and inhibit the progression of glioma by directly targeting PAK4." (PMID 32894165, 2020). "P21-activated kinase 4 (PAK4) is also a promoter of glioma growth." (PMID 39062119, 2024). "The involvement of PAK4 in anoikis resistance was confirmed by its experimental silencing, which led to increased anoikis and inhibition of glioma cell invasion and migration through downregulation of metalloprotease 2 (MMP2), alpha-v beta-integrin (Avß3) and epidermal growth factor receptor (EGFR)." (PMID 39062119, 2024). "Recent research reported that PAK4 interacted with PPARγ to regulate Nox1 in glioma." (PMID 34584017, 2021). "Given the close relationship of PAK4 function with glioma and NF-κB signaling, we wondered whether PAK4 also plays a role in neuroinflammation." (PMID 28680855, 2017). "Studies on PAKs in gliomas showed that PAK1 and PAK4 play an important role in the occurrence and development of GBM, and the abnormal activation of PAK1 is even more prominent." (PMID 36064705, 2022). "Besides this, a functional cooperativity between PAK4 and MMP2 has also been established in governing resistance to anoikis-mediated cell death, invasion, and migration in glioma." (PMID 28680855, 2017).
lung carcinoma (11 papers, 2015 to 2026). "LIMK1, a downstream effector of PAK4, has been reported to be up‐regulated in lung cancer and associated with high tumor metastasis and lymph node metastasis." (PMID 28440035, 2017). "The immunohistochemical expression of PAK4 in lung cancer was mainly observed in the cytoplasm of tumor cells, but a higher expression of c-PAK4 did not predict OS for patients." (PMID 36980457, 2023). "In lung cancer, a higher expression of the PAK4 gene, as indicated by microarray analysis, predicted shorter OS of non-small cell lung cancers, but the immunohistochemical expression of PAK4 did not predict the OS of patients." (PMID 36980457, 2023). "Several PAK4 inhibitors including PF-3758309 have also demonstrated that PAK4 is involved in the proliferation and migration of lung cancer cells." (PMID 36230657, 2022). "In this study, the authors found that TGFβ-induced FH-CSL interactions and cell growth arrest were significantly inhibited in lung cancer cells, which were reversed by PAK4 inhibition." (PMID 31435524, 2019). "siRNA-mediated gene silencing and protein kinase assay was applied to demonstrate the role and the mechanism of PAK4 in lung cancer cell migration, invasion." (PMID 25975262, 2015). "The PAK4 inhibitor PF-3758309 shows anti-metastatic effect in A549 human lung cancer cells and suppresses β-catenin pathways." (PMID 26068882, 2015). "The phosphorylation of fumarate by PAK4 counteracts its induced cell growth arrest in lung cancer." (PMID 36230657, 2022). "Moreover, PAK4 is highly expressed in lung cancer cells and clinical samples." (PMID 31435524, 2019). "In this study, the potential targets of Pinellia ternata highly overlap with lung cancer pathological genes, with FGFR4, CDK2, JAK2, KDR, PAK4, PTK2 and PDGFRA being the core." (PMID 42149884, 2026). "Among PAKs, PAK1, PAK2, and PAK4 exhibit a higher expression level in most cancer types; PAK1 and PAK4 are the most studied and better characterized, yet PAK2 has the highest alteration frequency among all PAKs, especially in lung cancer." (PMID 36429067, 2022).